FOXP3 (forkhead box P3)
Diseases named in the same sentence as FOXP3 in open-access papers (continued):
Sharing a sentence is not in itself a finding about the gene and the disease.
tumor (continued). "Conversely, the utility of RGB has been shown to selectively suppress the differentiation of CD4+Foxp3+ Treg cells, thereby inhibiting tumor growth." (PMID 40297580, 2025). "Sphingosine can regulate c-Fos, a direct target of Tregs, which affects the expression of target genes FoxP3 and PD-1 downstream of the transcription factor c-Fos, directly promoting Treg cell differentiation and suppressing tumor immunity." (PMID 40696413, 2025). "In general, positive/high FOXP3 expression was associated with better survival rates in TNBC patients, especially when focused on its presence in the tumor stroma." (PMID 39904885, 2025). "The correlation between higher expressions of FOXP3 and PD-1 with advanced pathological stages and poorer survival outcomes highlights their role in the immunosuppressive tumor microenvironment." (PMID 41375087, 2025). "This complex was selectively localized to the tumor and suppressed the accumulation of FoxP3+ regulatory T cells." (PMID 40943069, 2025). "Tregs, a specific subset of CD4+ CD25+ FoxP3+ T lymphocytes, suppress the anti-tumour immune responses and stimulate tumour growth." (PMID 40852716, 2025). "A significant correlation between FOXP3 knockdown in the tumor and in the blood at cycle 2, day 1, was observed for patients with a paired biopsy sample (R = 0.63; P < 0.05), supporting on-target ASO activity in both the tumor and periphery." (PMID 39937271, 2025). "The DUB USP7 is critical for Treg maintenance since inhibition or deletion of USP7 results in decreased FoxP3 protein stability and augmented anti-tumour immunity." (PMID 39929287, 2025). "This phenomenon is corroborated by the detection of CD73+Foxp3+Vδ1+ cells within the peripheral blood and the tumor microenvironment of breast cancer patients." (PMID 40141420, 2025). "P60, a Foxp3 inhibitory peptide, can hinder the regulatory T cell (Treg) activity and impair tumor proliferation." (PMID 39075226, 2025). "Forkhead box P3 (Foxp3) highly expressed Treg cells have an important function in limiting anti-tumor immunity." (PMID 40244052, 2025). "We found that the numbers of activated MDSCs (CD11b+Gr‐1+) and Tregs (CD4+CD25+Foxp3+) among the tumor‐infiltrating lymphocytes in the MAP treatment group were significantly reduced." (PMID 39499771, 2025). "Administration of recombinant Gal-1 or co-culture with Gal-1-expressing cells (e.g., tumor cells and trophoblasts) leads to the expansion of classical FOXP3+ CD25+ Tregs as well." (PMID 40178639, 2025). "The expression levels of FOXP3 and PD-L1 in tumor infiltrating Treg cells were significantly decreased." (PMID 40771692, 2025). "FOXP3 is a marker of regulatory T-cells, and these lymphocytes suppress the effector lymphocytes and thereby regulate the tumour immune response." (PMID 39883679, 2025). "During tumorigenesis, FoxP3+ Tregs inhibited antitumor immunity, promoted tumor escape and progression, and decreased immunotherapeutic efficacy." (PMID 40216744, 2025). "Lactate enhances CTLA-4 expression in tumor-infiltrating Treg cells by promoting USP39-mediated RNA splicing in a Foxp3-dependent manner, thereby sustaining Treg function in the tumor microenvironment." (PMID 40535811, 2025). "Patients with high FOXP3 expression on tumor-infiltrating lymphocytes (TILs) had a longer recurrence-free survival (RFS) compared to those with lower levels." (PMID 40507370, 2025). "Together, our results identify an inflammation-dependent requirement for continuous Foxp3 activity that can be exploited to selectively target tumor-infiltrating TREG cells." (PMID 40478934, 2025). "Preclinical studies have demonstrated the potential of FOXP3 ASO such as AZD8701 to target tumor-infiltrating Tregs." (PMID 39937271, 2025). "Higher FOXP3/CD8, FOXP3+PD-1/CD8, and CD32B/CD19 ratios were linked to more advanced disease features and shorter disease-free survival, suggesting a more immunosuppressive tumor microenvironment." (PMID 41375087, 2025).
tumor (continued). "proved that microwave ablation (MWA) combined with DEXs increased the quantity of CD8+ T cells and decreased the level of FOXP3+ Treg cells in tumor sites compared to MWA alone, thereby reshaping TIME." (PMID 40432919, 2025). "This divergence underscores the dual nature of B cells in cancer dynamics and collectively demonstrated that intratumoral IL-10+ Bregs suppressed CD8+ T-cell infiltration and cytotoxic function while promoting the induction of Foxp3+Tregs within the tumor." (PMID 41283510, 2025). "There were increased levels of FoxP3, vimentin, and L1CAM in PDAC cells, along with tumor-associated macrophage localization linked to tumor grades." (PMID 40699746, 2025). "In the one study (100%) that examined FOXP3 expression in the entire tumor area, there was a trend of better survival in patients with high FOXP3 expression." (PMID 39904885, 2025). "Our results showed that after the application of AZD5582, the expression level of CD8+ T cells was increased locally in the tumor, while the expression level of Foxp3+ regulatory T cells was decreased." (PMID 39917292, 2025). "We found a significant reduction of CD4+Foxp3+ T cells in the LLC tumor bed of maraviroc-treated mice." (PMID 40553564, 2025). "On day 5 after tumor implantation, tumor-bearing mice were treated daily with 5-ph-IAA to induce Foxp3 degradation." (PMID 41062655, 2025). "Compared to the NQO1 group, the combined Plerixafor group indicated significantly increased infiltration of CD3+ T cells in the tumor tissue, while the infiltration of Treg cells (FOXP3+CD4+ and FOXP3+CD25+CD4+) was significantly reduced." (PMID 41028931, 2025). "We found that the proportion of CD4+CD25+FoxP3+ Tregs in the tumor tissues was remarkably decreased in the ICD 4T-1 cells group compared to that in the PBS group." (PMID 40283929, 2025). "Immunohistochemical analysis showed that lacidipine (0.5, 1, and 20 mg kg−1) in combination with DOX/cisplatin increased CD8 expression and decreased Foxp3 expression in tumor tissues." (PMID 39585774, 2025). "Flow cytometry analysis showed that chimera treatment exhibited a significant reduction in both the frequency and absolute number of FoxP3+CD4+ Treg cells per milligram of tumor tissue compared to the PBS control group." (PMID 41402667, 2025). "The regulatory subset of γδ T cells that express the transcription factor forkhead box p3 (Foxp3), termed γδ regulatory T cells (γδ Tregs), has been confirmed to be at low frequencies in tumor-infiltrating leukocytes (TILs) and human PB." (PMID 40236710, 2025). "Conversly, the presence of immunosuppressive cells such as regulatory T (Treg) FOXP3+ cells can impair the anti-tumor response which is correlated with a poor prognosis in melanoma patients treated with ICIs." (PMID 40554927, 2025). "Immunohistochemistry for Foxp3 in the tumor tissue was performed, and the serum IgG4 level was measured." (PMID 40563656, 2025). "CD4+CD25+Foxp3+ Tregs are recruited and expanded in tumors and constitute an important mechanism utilized by tumor cells to evade protective immunity and support metastatic growth." (PMID 40244064, 2025). "Literature has reported that endurance training can inhibit the recruitment of FoxP3+ Tregs cells in tumors, hence enhancing anti-tumor immunity." (PMID 41480347, 2025). "CD4+/Foxp3+ Tregs were found embedded in the tumor mass or in the perivascular area, occasionally close to the CRATER edges but rarely inside." (PMID 41109214, 2025). "The total Treg count correlates with PTC and FTC aggressiveness, while tumor size inversely correlates with FoxP3 expression." (PMID 40136652, 2025). "This contrasts to total CD4+ T-cells and FoxP3+ Tregs, both of which were highest in the 10–20 μm category, thus residing further away from tumour cells compared to total CD8+ T-cells." (PMID 41310655, 2025). "The underlying mechanism involve increased infiltration of FOXP3+ and CD4+ Treg cells and CAFs within the tumor microenvironment." (PMID 41235229, 2025).
tumor (continued). "For example, a study revealed that the depletion of myCAFs increased CD4+Foxp3+ Tregs infiltration into tumor, leading to an aggressive tumor progression." (PMID 40248695, 2025). "first showed in a mouse model that metformin treatment increased CD8+ T‐cell infiltration and FoxP3+ regulatory T‐cell infiltration in the tumor microenvironment, using mEERL95 cells, which are mouse‐derived HPV‐positive HNSCC models." (PMID 40387523, 2025). "FoxP3 (Treg) expression progressively increased throughout tumor progression (normal tissue → AAH/AIS → MIA → IAC)." (PMID 41417416, 2025). "Our study assessed bulk tumor mRNA which captures expression from both tumor and immune cells, whereas IHC methodology can distinguish between FOXP3+ Tregs and FOXP3+ tumor cells." (PMID 40806346, 2025). "To assay the impact of Lac on Tregs in tumor microenvironment, we lethally irradiated these mice, followed by reconstruction of the immune system with bone marrow of FOXP3-DTR-GFP mice." (PMID 39979425, 2025). "In contrast, low-risk genes (CCL17, CXCL8, FOXP3, CCR7) inhibit tumor progression by modulating immune cell infiltration and activity." (PMID 40517358, 2025). "FOXP3 knockdown experiments showed reduced cell proliferation and migration, highlighting its role in tumor progression." (PMID 39883234, 2025). "Both stromal TILs (sTILs) and those at the invasive front increase with tumor grade, while the presence of FOXP3+ regulatory T cells correlate with higher malignancy." (PMID 41230456, 2025). "Some investigators have demonstrated that IL-2 production by CD8+ T cells indirectly upregulates anti-apoptotic molecules on the surface of conventional CD4+Foxp3+ Tregs in the tumor microenvironment to promote tumor growth." (PMID 40553564, 2025). "We observed that a robust TAAs expression together with a favorable immune infiltrate contexture inside the tumor (high intratumoral CD8 + cells/low FOXP3 + Treg and CD163 + myeloid cells) improve the vaccine ability to protect pts from cancer recurrence." (PMID 40251644, 2025). "Changes in FOXP3 mRNA expression levels from baseline in tumor samples were available for 13 patients treated with AZD8701 monotherapy." (PMID 39937271, 2025). "We analyzed changes in FOXP3 mRNA in baseline and on-treatment tumor samples as a predefined secondary endpoint based on a strong scientific rationale for identifying the biological activity of an ASO directed against FOXP3." (PMID 39937271, 2025). "On day 5 post tumor implantation, the tumor-bearing mice were treated daily with 5-ph-IAA to induce Foxp3 degradation." (PMID 40470210, 2025). "The proportion of CD25+Foxp3+ Treg cells among activated CD4+ T cells was markedly reduced when co-cultured with TBX21-silenced tumor cells compared with sh-NC controls." (PMID 41573646, 2025). "In an MC38 model, thiostrepton treatment reduced intratumoral Foxp3+ Tregs and significantly inhibited tumor growth." (PMID 40820379, 2025). "We specifically noted that CD8+FoxP3+ cells and their subsets were within 30 μm of a significant number of tumor cells." (PMID 40422521, 2025). "Further analysis revealed that high ALG3 expression was associated with reduced infiltration of CD8+ T cells and CD68+ macrophages in both tumor and stromal areas, while positively correlating with increased infiltration of FOXP3+ regulatory T cells (Tregs)." (PMID 40475760, 2025). "FOXP3+ Tregs inhibit antitumor responses, while ablation of FOXP3+ Tregs dramatically reduces tumor growth." (PMID 40843360, 2025). "There is compelling evidence that FoxP3+ regulatory T cells (Tregs) play a critical role in promoting tumor immune evasion." (PMID 40038776, 2025).
tumor (continued). "These effector immune cells are suppressed via multiple mechanisms regulated by the transcription factor Foxp3—mechanisms that are frequently co-opted by tumours to escape immune surveillance." (PMID 40649307, 2025). "Kynurenine secreted by tumor cells inhibits T cell activation and proliferation and induces Forkhead box P3 (FoxP3) expression, which is critical for the differentiation and function of Treg cells." (PMID 40035950, 2025). "We examined CD4+Foxp3− Tconv and iTr35 in the spleen and blood by flow cytometry after sorting, CD4+Foxp3− Tconv expression was increased in tumor-bearing mice." (PMID 40259042, 2025). "In the tumor tissues of the Hepa1-6 KO cells, the number of Foxp-3+ Treg cells decreased, while the number of granzyme B (GZMB)+ T cells increased without upregulating exhaustion markers such as PD-1 and TIM-3." (PMID 40139191, 2025). "FOXP3 is a transcription factor with a dual role in cancer biology, functioning as an immune suppressor in certain tumors and as a direct regulator of tumor cell behavior in others." (PMID 39883234, 2025). "CCL11 was shown to increase the CD4+CD25+Foxp3+ Tregcells proportion, CCR3 and Foxp3 expression, and the release of IL-2 andtransforming growth factor (TGF) β1 in non-tumor-associated CD4+ T cells through the STAT5 signalingpathway." (PMID 40026499, 2025). "An additional microenvironmental factor is TGF-B-induced immune escape, e.g., by recruiting FOXP3+ T-cells, and thereby turning the tumour into a “cold cancer” with worse outcome." (PMID 40826447, 2025). "Tumor-associated M2 macrophages and CD4+ CD25+FoxP3+ regulatory T-cells (Tregs) suppress anti-tumor immune responses through secretion of immunosuppressive cytokines IL-10 and TGFβ, and presentation of CTLA4 on T cells and PD-L1 on macrophages." (PMID 40831543, 2025). "Mechanistic studies further demonstrate that exposing tumor cells to hCG augments FOXP3 expression and increases Treg differentiation, indicating that CGB5-mediated signaling is a key driver of the immune-evasion phenotype." (PMID 41048937, 2025). "In aged OVX 67NR tumor-bearing mice, tacalcitol decreased Il17a expression, while calcitriol reduced Foxp3 expression." (PMID 40894304, 2025). "Among key regulators of anti-tumor immunity, PD-L1, PD-1, FOXP3, and miR-155 have emerged as key modulators of immune evasion and tumor progression in several malignancies, including OSCC." (PMID 40806346, 2025). "The regulatory subset of γδ T cells that express Foxp3, termed γδ Tregs, has been reported to be at a low expression frequency in tumor-infiltrating leukocytes and human PB." (PMID 40236710, 2025). "To evaluate the relationship between FOXP3 mRNA expression and tumor progression, we analyzed FOXP3 levels across clinical stages I–IV in both our experimental MMA cohort and the TCGA validation dataset." (PMID 40806346, 2025). "TGFB facilitates the conversion of naive CD4+ T cells into CD4+Foxp3+ regulatory T-cells (Tregs), which inhibit anti-tumor immunity, thereby promoting tumor progression." (PMID 40565031, 2025). "The infiltration abundance of regulatory T cells (Tregs, Foxp3+) in the tumor microenvironment of male patients is higher, indicating stronger immunosuppression, and male patients tend to have M2 macrophage polarization." (PMID 40469187, 2025). "In the end, IL-35+ Bregs hindered the infiltration of CD8+ T cells, reduced TNF and IFN-γ cytokines production by CD4+ T cells, and promoted the accumulation of Foxp3+Tregs within the tumor." (PMID 41283510, 2025). "In epithelial ovarian cancer, for example, the chemokine CCL22 recruits CD4+CD25+FOXP3+ cells, leading to suppression of antitumor immunity and favoring tumor progression." (PMID 41394821, 2025). "Tregs, marked by CD25 and FOXP3, maintain immune tolerance but promote tumor progression in the TME." (PMID 40242773, 2025). "FOXP3+Tregs play a crucial role in maintaining immune balance and are vital suppressors of anti-tumor immune responses." (PMID 38047300, 2024).
tumor (continued). "In mouse, the principal mechanism for increasing CD4+ CD25+ presenting FOXP3+ population in the tumor site is via the conversion of CD4+ CD25- T cells." (PMID 38571964, 2024). "The ratio of Tregs to the total immune infiltration was assessed as the ratio of FoxP3 (200x magnification) to CD3-positive cells (400x magnification) in the tumor center and periphery." (PMID 39650654, 2024). "The tumour immune microenvironment (TIME) was characterised by high CD4, CD8, Foxp3, and PD-L1 levels, associating with better pathological regression (TRS0/1)." (PMID 39164491, 2024). "FoxP3+ TILs were found in higher quantities in tumor samples from patients who achieved pNR compared to those who achieved pCR." (PMID 39703499, 2024). "CD8+ TILs, PD‐L1 expression, and accumulation of CD4+CD25+FOXP3+ Tregs are involved in immune homeostasis, tumor proliferation, and metastasis." (PMID 39264227, 2024). "For FOXP3, the deviation of biopsy or tumor surface T-cell density from the interquartile range of the tumor center is higher than for CD8, and mostly in the tumors with the lowest T-cell densities in the resection." (PMID 39444424, 2024). "FOXP3+ Tregs are present in the tumor microenvironment (TME) where they promote tumor development and progression by the cytokine releasing and suppressing activity of cytotoxic T cells." (PMID 38674427, 2024). "In various cancer models in mice, USP22 specificity ablation has been demonstrated to impede tumor growth by reducing FOXP3 protein levels." (PMID 39144146, 2024). "Despite the fact that several studies have demonstrated that FOXp3 Tregs play a role in tumor growth, a recent study discovered that the two unique populations of Tregs, FOXp3 low and FOXp3 high, play different roles in tumor promotion." (PMID 39257589, 2024). "Compared with that in simple nodular goiter tissue, the FoxP3+ Treg cell number in PTC tumor tissue is greater, and it is positively correlated with disease stage." (PMID 39534095, 2024). "To analyze systemic effects of ASO FOXP3 targeting of Tregs in tumor bearing mice, we performed immune profiling of the spleens." (PMID 39234236, 2024). "In 275 tumor specimens from patients with endometrial cancer, high FOXP3 expression was correlated with poor OS." (PMID 38318526, 2024). "In the MCa-M3C mouse model, increased CD8+ T cell and DC (Gr-1+CD11c+) numbers and decreased Treg cell numbers (CD4+FOXP3+) in tumor tissues, and increased CD8+ T cell numbers in spleens were found in IR + DSF/Cu-treated mice." (PMID 38678042, 2024). "Tumors that presented a concurrent high expression of TGFβ/FoxP3, TGFβ/VEGF, and TGFβ/CD31 markers were statistically significantly associated with parameters of tumor malignancy (high HGM, presence of vascular emboli and nodal metastasis)." (PMID 39165025, 2024). "These T cells, according to our observation, are positioned more proximal to tumor cells in comparison to CD3+FoxP3+ T cells." (PMID 38375478, 2024). "Among patients with SQ-LC surgically resected in our institution between 2011 and 2017, those with pathological stage IA3-IIIA were immunohistochemically studied to evaluate Foxp3 + TILs in their tumor stroma." (PMID 38402536, 2024). "In this study, we demonstrated that only the densities of CD3+CD4+Foxp3+ T cells (Tregs) on the tumor bed were significantly decreased and almost disappeared in post-NAC tissue compared with pre-NAC tissue in those with pCR." (PMID 38228697, 2024). "Populations of FOXP3+ Treg have been confirmed mediators in angiogenesis and immune-suppressive functions, contributing to the pro-tumor TME25, although a recent study stated the role of Th2 cells in anti-tumorigenic responses." (PMID 39075108, 2024). "PD-L1 IC and CPS ≥10% was more often detected in tumours with greater number of tumour-infiltrating CD4+Foxp3+ T cells (p = 0.01 and p = 0.025, respectively)." (PMID 38541208, 2024).